INS (insulin)
Diseases named in the same sentence as INS in open-access papers (continued):
Sharing a sentence is not in itself a finding about the gene and the disease.
diabetes (continued). "Moreover, the Akt substrate Forkhead box protein O1 (FoxO1) is involved in the regulation of proliferation and apoptosis, so the insulin signaling network has a major role not only in obesity and diabetes but also in cancer." (PMID 27149630, 2016). "In conclusion, this study shows that liver mitochondrial dysfunction is not strongly associated with the establishment of diabetes in this insulin‐resistant rat model." (PMID 26847727, 2016). "Recently, researchers from Harvard Stem Cell Institute (HSCI) found a new hormone and named it betatrophin, which, closely related to diabetes treatment, could increase the quantity of cells that produce insulin in mice quickly." (PMID 27242389, 2016). "A further increase in those requiring insulin was observed, which was associated with diabetes severity, rather than with the use of exogenous insulin itself." (PMID 27887576, 2016). "However, misclassification of diabetes type was possible and was more likely to affect patients prescribed insulin monotherapy." (PMID 27152598, 2016). "Diabetes patients treated with pharmacotherapy including oral hypoglycemic agent and insulin were more likely to be older, have hypertension, less physically active, and more obese, but less likely to be current smokers or frequent alcohol consumers than non-diabetes study subjects (all p <0.01)." (PMID 27105059, 2016). "Taken together, it seems that the reduction in venous compliance in diabetes is caused by long-term effects of diabetes rather than short-term differences in blood glucose or insulin." (PMID 27708615, 2016). "It is tempting to suggest that the decreased clearance of circulating DMAAs postprandially, as a result of impaired tissue uptake, might reflect the insulin resistant and diabetes prone phenotype." (PMID 27274867, 2016). "All participants, but especially the physicians, regarded the measurements as essential for following up and adjusting diabetes treatment, but they admitted that they were most useful for residents with unstable blood glucose levels, or for residents in need of rapid-acting insulin." (PMID 26855612, 2016). "However, in 15 cases, the anti-diabetes medication had to be reduced gradually during the study period, and in two cases, including one on insulin treatment, the medication was cancelled." (PMID 27664051, 2016). "In addition, circRNAs can oversee cellular metabolism and disorders such as diabetes mellitus through the regulation of insulin signaling as well as limit tumor progression through Wnt signaling and β-catenin pathways." (PMID 27642518, 2016). "In clinical practice, emphasis is often placed on BMI to help differentiate between type 1 and type 2 diabetes but the study findings presented here indicate that, among patients treated with insulin, time to insulin and age at diagnosis are better predictors of diabetes subtype than BMI." (PMID 27080317, 2016). "Diabetes is a chronic disease that represents a serious public health problem and occurs either when the pancreas does not produce enough insulin or when the body cannot effectively use the insulin it produces." (PMID 27651798, 2016). "These stage 2 beta cells still secrete insulin in response to high extracellular potassium, which is consistent with effectiveness of sulfonylureas (potassium channel blockers) for treating diabetes." (PMID 27048248, 2016). "67.5 % had diabetes for less than 10 years and 40 % were on insulin therapy." (PMID 26732585, 2016). "Efficacy in controlling diabetes onset in the Ins2−/− NOD mouse model defined by a T cell repertoire directed essentially toward insulin by immunization with a thioreductase-containing GAD65 peptide further anticipates a bystander effect toward alternative antigens." (PMID 26973647, 2016).
diabetes (continued). "Betatrophin, mainly circulated in liver and adipose tissues, promotes greatly the proliferation of pancreatic beta cells, plays an important role in modulating glycolipid metabolism, and maybe replaces insulin in the effective treatment of diabetes." (PMID 27242389, 2016). "Additionally, a potential role of insulin was noted in the development of hypertension, atherosclerosis and cancer in patients with diabetes." (PMID 27906989, 2016). "Elevated incidence of diabetes onset in this model is hypothesized to be related to altered recognition of proinsulin and enlarged T cell repertoire specific of insulin in the periphery." (PMID 26973647, 2016). "Diabetes mellitus is one of the most common metabolic diseases caused by high blood glucose and lack of insulin production or sensitivity, which influence body system functions." (PMID 26980377, 2016). "The abnormality of insulin action may be an explanatory factor for the alteration in serum FGF23 levels in the first-degree relatives of patients with diabetes." (PMID 27698482, 2016). "The worse prognosis in CRT-treated T2DM may be due mainly to the higher mortality of patients with insulin-treated diabetes." (PMID 26636106, 2016). "Both are characterised by insulin resistance and insulin hypo-secretion and share similar risk factors including increased age, family history of diabetes and non-white ethnicity." (PMID 26789123, 2016). "Reduced PPAR-α, -β/δ, -γ, PGC-1α, and PGC-1α in the diabetes state is followed by increased insulin tolerance and reduction of fatty oxidation in skeletal muscle, 29 due to their in glucose transport to skeletal muscle and mitochondrial function of skeletal muscle." (PMID 27508153, 2016). "Attending camp for children and adolescents living with diabetes is associated with a significant decrease in HbA1c twelve months after camp without changes in insulin doses." (PMID 26791079, 2016). "In this report they demonstrated that H2S impairs insulin mediated glucose uptake and that high fructose-induced diabetes led to increased production of H2S in epididymal adipose tissue, an effect that could be blocked by inhibiting CSE." (PMID 27478532, 2016). "Few studies have examined the impact of endometrial cancer risk factors, such as obesity, diabetes, and nonuse of aspirin on the insulin/IGF and sex hormone axes in normal endometrial tissues." (PMID 27125830, 2016). "Impaired glucose tolerance and reduced insulin sensitivity are hallmarks of diabetes and obesity." (PMID 27180971, 2016). "Diabetes is a disease reaching a global epidemic, which results from dysfunction to the islets of Langerhans in the pancreas and their ability to secrete the hormone insulin to regulate glucose homeostasis." (PMID 27681078, 2016). "Thirdly, the urinary Mg level was not measured either, further studies should combine the factor of urinary Mg to confirm the hypothesis that insulin resistance was responsible for the low concentration of serum Mg in diabetes subjects." (PMID 27756380, 2016). "Novel drugs targeting insulin signaling and Wnt signaling pathways are expected to prevent and intervene in the glucose metabolism disease programming to reduce the global burden of diabetes." (PMID 27782077, 2016). "Thus, detection of insulin is necessary for early disease diagnosis and therapy monitoring of diabetes or insulinoma." (PMID 26784202, 2016). "Moreover, serum insulin levels in DM rats were (ng/ml): 4.2 ± 0.3 and 0.09 ± 0.03 (p<0.001) before and 9 weeks after diabetes induction, respectively." (PMID 27101382, 2016). "Our study nevertheless highlights insulin treatment, insulin-sensitising agents, baseline HbA1c and baseline serum insulin as important clinical features, and also points to a higher likelihood of diabetes remission for patients with a less severe diabetes." (PMID 29263820, 2016). "However, in the case presented the mother denied chronic use of medications apart from insulin injections for her diabetes." (PMID 27998308, 2016).
diabetes (continued). "Destruction of beta cells by STZ causes an absolute deficiency of insulin, which resembles type 1 diabetes mellitus in men, although without involvement of the immune system as an executor of destruction." (PMID 27803936, 2016). "Similarly, in older and younger subjects, pioglitazone was equally effective in improving insulin sensitivity, a major factor contributing to diabetes prevention." (PMID 27585671, 2016). "Therefore in the later stages of diabetes mellitus, the levels of insulin in the body start depleting." (PMID 27151376, 2016). "Among patients with hypercholesterolemia, 22% (12 of 55) were taking lipid-lowering medication (HMG CoA reductase inhibitors) and 22% (12 of 55) were taking medication to control diabetes (metformin, 4%; sulfonamide urea, 4%; and insulin, 14%) at the start of the study." (PMID 27287020, 2016). "Moreover, diabetes effects on the testicular tissue have been attributed to insufficient production of insulin which in turn results in decreasing the endocrine function of both Leydig and Sertoli cells." (PMID 27679827, 2016). "Diabetes-specific data were: diabetes duration 16.9 ± 8.1 years, HbA1c 7.4% ± 0.6% (57 ± 6.3 mmol·mol−1), c-peptide 0.13 ± 0.19 nmol·L−1, carbohydrate factor 12 ± 4.9 g, and total daily insulin dose 41 ± 16 U." (PMID 27517956, 2016). "Among adults with diagnosed diabetes (type 1 and type 2), self-reported data captured through national surveys suggest 86% (17.9 million) used oral medication or insulin to control glycemic levels, 71% used medication for hypertension, and 65% used medication for hypercholesterolemia." (PMID 27895533, 2016). "Insulin resistance in diabetic patients may vary depending on the duration of diabetes mellitus, use of oral hypoglycemic agents or insulin, and glycemic control status." (PMID 27128847, 2016). "Accordingly, manganese supplementation may enhance MnSOD activity and protect against diabetes by enhancing insulin secretion." (PMID 27258818, 2016). "Maturity onset diabetes of the young (MODY) is a monogenic form of diabetes caused by a mutation in a single gene, often not requiring insulin." (PMID 26059258, 2016). "Failure of the β-cell to compensate for the increased insulin demand in obesity eventually leads to diabetes; as a result of the complex interplay of genetic and environmental factors (e.g. ongoing inflammation within the islets) and impaired vascular function." (PMID 27617438, 2016). "Ins2-deficient (Ins2KO) NOD mice develop diabetes at an accelerated rate, as do HLA-A∗02:01-transgenic Ins2KO NOD mice, and both Ins2-deficient strains have increased insulin-specific islet-infiltrating CD8 T cells compared to their wild-type (WT) counterparts." (PMID 26824049, 2016). "Hypoglycaemia is a common adverse effect of insulin and sulphonylurea treated Diabetes Mellitus." (PMID 26893294, 2016). "In the treatment of diabetes, Res can cause dose-dependent hypoglycemic effect and improve the insulin levels of diabetic rats induced by STZ in order to enhance the glucose uptake, reducing blood glucose levels by improving insulin sensitivity." (PMID 27806317, 2016). "In the last years several genome wide association studies have indicated that genes expressed in beta cells, and potentially involved in insulin secretion, might play an important role on the onset of type 2 diabetes mellitus." (PMID 27667715, 2016). "Alcohol may have positive effects, such as protecting against diabetes by increasing insulin sensitivity, changing levels of alcohol metabolites, increasing HDL concentrations, or the anti-inflammatory effect of alcohol." (PMID 26981121, 2016). "TSC22D4 thus represents a previously unknown checkpoint in inter-organ communication and systemic metabolic control and may serve as an attractive target in insulin sensitizing diabetes therapies." (PMID 27827363, 2016).
diabetes (continued). "This concept of heterogeneity in the autoimmune process is consistent with recent evidence from The Environmental Determinants of Diabetes in the Young study that, in infancy, the initiation of autoimmunity to GAD and insulin differ in both timing and HLA associations." (PMID 26676824, 2016). "Prospective studies published in English, Portuguese and Spanish from 2002 to 2014, evaluating the effect of insulin on weight parameters, body mass index and pulmonary function in patients with cystic fibrosis, with a mean age of 17.37 years before the diabetes mellitus phase were included." (PMID 26994743, 2016). "The CADTH recommendations were criticized by the Canadian Diabetes Association (CDA) for undervaluing the merits of self-management in non-insulin-treated patients and for not accounting for the increased risk of hypoglycemia associated with secretagogues." (PMID 26972690, 2016). "Thus, we determined the effects of exenatide on glucose tolerance, β-cell function, and insulin sensitivity in a canine model of pre-diabetes." (PMID 27398720, 2016). "Taken together, the insulin implants facilitate the management of diabetes mellitus in rats." (PMID 27253523, 2016). "This cross-sectional study indicated that increased serum TC level might be related to the decrease of insulin secretory capacity in aged healthy population and that reduction of TC is more necessary in obese subjects to prevent diabetes." (PMID 26881755, 2016). "MiR-30d also plays a key role in activating glucose-induced insulin gene transcription and in avoiding beta-cell functions impaired by pro-inflammatory cytokines, which may act as a potential target for diabetes intervention." (PMID 28066696, 2016). "Participants with T1D had mean diabetes duration of 8.8 ± 3.0 years and 55 % were on insulin pumps." (PMID 27099615, 2016). "The ITT is performed under supervision by intravenous injection of 0.15 units/kg (0.1 units/kg if high suspicion of hypocortisolism, 0.2units/kg in insulin resistant states such as diabetes mellitus or acromegaly) soluble insulin with measurement of plasma cortisol at 0, 30, 45, 60, 90 and 120 min." (PMID 27316460, 2016). "Furthermore, the following genes are involved in diabetes and insulin signaling: MDH2, PPP1CA and HRAS." (PMID 26938218, 2016). "Furthermore, the ELISA experiment showed that both the gene transfection and insulin delivery were jointly contributed to the enhancement of insulin release level, which was in favor of diabetes treatments." (PMID 26948978, 2016). "This treatment might also be considered in some human diabetes patients with diminished insulin reserve." (PMID 28702245, 2016). "However, as expected, current smoking, prior history of diabetes, hypertension, high insulin and glucose levels, and lower HDL predicted an increased risk of CHD." (PMID 27511193, 2016). "Insulin implants were applied 2 weeks after induction of diabetes with STZ." (PMID 27253523, 2016). "It appears that hyperlactacidemia may function as an interaction hub between diabetes and cancer and contribute to a higher insulin resistant status and a more malignant phenotype of cancer cells." (PMID 28077918, 2016). "Together, the experiments suggest that blocking glucagon could be a useful treatment for diabetes, but only in individuals who still have some insulin-producing cells." (PMID 27092792, 2016). "In addition to blocking the renin-angiotensin system, telmisartan acts as a selective modulator of PPARγ, a central regulator of insulin and glucose metabolism and a well-known target of insulin-sensitizing drugs used to treat type 2 diabetes mellitus." (PMID 26846539, 2016). "Currently, some studies have examined the roles of lncRNAs in diabetes, and the emerging evidence indicates that lncRNAs may be involved in maintaining pancreatic beta cell function and insulin signal transduction, which may affect diabetes development." (PMID 27698546, 2016).
diabetes (continued). "They assessed the improvement in the contractile strength after a prolonged ischemic insult followed by reperfusion in myocardial tissue from patients with diabetes taking insulin, those taking oral antidiabetic drugs (glibenclamide or glipizide), and patients without diabetes." (PMID 27656659, 2016). "The first point is what most insulin pump users and diabetes healthcare professionals have experienced in practice: that in conditions where blood glucose levels are low–normal at the start of exercise, reducing basal insulin delivery (even by 50%) does not always mitigate against hypoglycaemia." (PMID 27287376, 2016). "After adjustment for age, gender, ethnicity, diabetes duration, HbA1c, body mass index, insulin treatment, number of anti-hypertensives, history of peripheral vascular disease, and baseline eGFR (R2 0.87), baseline foot insensitivity was associated with study-end eGFR (B = −3.551, p = 0.036)." (PMID 27876022, 2016). "Impaired glucose tolerance and diabetes may present in these patients particularly during puberty when insulin response to hyperglycemia is blunted." (PMID 26758964, 2016). "Currently diabetes is controlled by diet, exercise, oral hypoglycemic agents and insulin therapy." (PMID 27846886, 2016). "Decreased insulin secretion and increased insulin resistance are related to the onset of diabetes." (PMID 27612202, 2016). "Our results demonstrate that the simultaneous insulin drug delivery and insulin gene transfection in a controlled mode may have great potential in the clinical diabetes treatments." (PMID 26948978, 2016). "The fetal insulin hypothesis aims to provide a link between low birth weight from malnutrition and beta cell dysfunction and type 2 diabetes mellitus." (PMID 27664190, 2016). "Finally, insulin beliefs refer to patients' beliefs about insulin and have been found to play an important role in adherence to treatment and diabetes control." (PMID 26682231, 2016). "Therefore, this study was conducted to assess the effect of maternal diabetes on the cardiac development of albino rat fetuses and the roles of prenatal zinc/or insulin administration in counteracting this effect." (PMID 26925289, 2016). "For those with insulin-requiring diabetes there may be additional obstacles to be overcome, to ensure regular supplies of affordable insulin, needles and glucometers." (PMID 26913752, 2016). "Taken together, our results qualify the subchronic STZ-model together with the insulin dosing regimen as a suitable model for the study of drugs for the treatment of type 1 diabetes in combination with insulin and possible longterm complications of diabetes, i.e. early signs of diabetic nephropathy." (PMID 27253523, 2016). "Earlier studies have identified a point mutation in the mitochondrial gene in a family with slowly progressive insulin-dependent diabetes mellitus (IDDM) or insulin-deficient non-IDDM." (PMID 27350825, 2016). "Although endocrinologists and diabetes specialists will continue to maintain expertise in this field, it behooves the primary care physician to have a working knowledge of insulin pumps and sensors to ensure optimal clinical care and decision-making for their patients." (PMID 26742082, 2016). "Previous research has demonstrated that TNFα can interfere with insulin mediated glucose metabolism in neonatal porcine adipose tissue, thereby creating an insulin resistant state that is characteristic of adipose tissue inflammation in obesity, diabetes and metabolic syndrome." (PMID 27087941, 2016). "Thus, STZ reduces rat body weights including testes, and, like insulin, SeNPs increase the weight of the testes in rats even in those affected due to diabetes." (PMID 27869771, 2016). "The insulin treatment prevented all diabetes induced alterations (resp)." (PMID 26955430, 2016).